MFNG (MFNG O-fucosylpeptide 3-beta-N-acetylglucosaminyltransferase)
Description:
Glycosyltransferase that initiates the elongation of O-linked fucose residues attached to EGF-like repeats in the extracellular domain of Notch molecules (By similarity). Modulates NOTCH1 activity by modifying O-fucose residues at specific EGF-like domains resulting in inhibition of NOTCH1 activation by JAG1 and enhancement of NOTCH1 activation by DLL1 via an increase in its binding to DLL1 (By similarity).
Tractability: Antibody: UniProt predicts a signal peptide or a membrane-spanning region. PROTAC: ubiquitination databases record sites on it.
Gene: Protein-coding gene on chromosome 22 (37,469,063 to 37,486,402, reverse strand). Ensembl gene ENSG00000100060.
Subcellular location: Golgi apparatus membrane
Subcellular location (Human Protein Atlas): Vesicles
Pathways (Reactome):
Signal Transduction: Pre-NOTCH Processing in Golgi
Gene Ontology:
Molecular function: O-fucosylpeptide 3-beta-N-acetylglucosaminyltransferase activity; glycosyltransferase activity
Biological process: marginal zone B cell differentiation; pattern specification process; regulation of Notch signaling pathway
Cellular component: extracellular region; Golgi membrane; membrane
Genetic constraint (gnomAD): Loss-of-function variants: 26 observed, 34.52 expected, observed/expected ratio (o/e) 0.75, 90% interval 0.55 to 1.04. The upper end of that interval is the gene's LOEUF score, 1.04, which puts it in group 4 of 6, group 1 being the genes least tolerant of losing a copy. Missense variants: 383 observed, 431.07 expected, observed/expected ratio (o/e) 0.89, 90% interval 0.82 to 0.97. Synonymous variants: 158 observed, 182.42 expected, observed/expected ratio (o/e) 0.87, 90% interval 0.76 to 0.99.
Homologues: Orthologues: chimpanzee MFNG (98% identical), macaque MFNG (97% identical), pig MFNG (89% identical), mouse Mfng (83% identical), rat Mfng (83% identical), rabbit MFNG (74% identical), dog MFNG (66% identical), guinea pig MFNG (55% identical), zebrafish mfng (55% identical), Drosophila melanogaster fng (40% identical). Paralogues in human: LFNG (59% identical), RFNG (52% identical), B3GLCT (20% identical).
Diseases named in the same sentence as MFNG in open-access papers:
MFNG is named in the same sentence as 22 diseases in open-access papers, as found by Europe PMC text mining. Sharing a sentence is not in itself a finding about the gene and the disease. The quoted sentences say what the papers report.
breast carcinoma (6 papers, 2015 to 2023). "MFNG is overexpressed in breast cancer and renal cell carcinoma and is associated with poor prognosis." (PMID 36575396, 2022). "We previously demonstrated that the elevated expression of manic fringe (MFNG) plays a pivotal role in breast cancer." (PMID 35804829, 2022). "Previous studies have shown that LFNG decrease could be used as a biomarker in basal-like mammary tumors, while MFNG functions as an oncogene in breast cancer and contributes to the aggressiveness of CLBC." (PMID 37932706, 2023). "MFNG is a kind of glycosyltransferases that activates Notch signaling and plays an important role in breast cancer, whereas inhibition of MFNG may attenuate the triple-negative breast cancer." (PMID 36925638, 2023). "It was reported that MFNG could promote the malignancy of breast cancer by activating Notch signaling; therefore, we evaluated whether the ectopic expression of MFNG could activate Notch signaling." (PMID 35804829, 2022). "While our previous work demonstrated the oncogenic role of MFNG in claudin-low breast cancer by modulating the Pik3cg-driven Notch signaling, the precise mechanism as to how MFNG can be regulated in TNBC has not been reported elsewhere." (PMID 35804829, 2022). "GATA3 is a known transcription factor that controls the expression of several genes in the breast cancer; therefore, we presumed that GATA3 could regulate the transcription of MFNG." (PMID 35804829, 2022). "MFNG expression in human breast cancer is highly correlated with the expression of NOTCH4, but not other Notch receptors." (PMID 26682266, 2015). "In the clinical breast cancer tissues, IHC staining revealed a consistent expressing pattern in TNBC and statistical analysis showed a negative correlation between GATA3 and MFNG expression in TNBC." (PMID 35804829, 2022).
sarcoma (2 papers, 2021 to 2023). A usually aggressive malignant neoplasm of the soft tissue or bone. "High expression of MFNG was also indicative of poor prognosis in patients with LUAD, thymoma (THYM), uterine corpus endometrial carcinoma (UCEC), endocervical adenocarcinoma (CESC), (sarcoma) SARC, and THYM." (PMID 37932706, 2023). "Compared to the non-tumor tissues, the expression levels of both IRF-1 and MFNG were significantly lower in 11 types of sarcoma including leiomyosarcoma, myxoid/round cell liposarcoma, and malignant fibrous histiocytoma." (PMID 34277600, 2021).
adenoma (1 paper, 2018). A neoplasm arising from the epithelium. "Addiction to Jag1 is concomitant with the absence of Manic Fringe (MFNG) in adenoma cells, and its ectopic expression reverts Jag1 dependence." (PMID 30065304, 2018). "In contrast, MFNG was detected in most of the non-transformed organoid structures and notably absent in the ApcMin/+ adenoma spheroids." (PMID 30065304, 2018).
autoimmune disease (1 paper, 2025). A disorder resulting from loss of function or tissue destruction of an organ or multiple organs, arising from humoral or cellular immune responses of the individual to their own tissue constituents. "Through its regulation of Notch signaling, MFNG influences immune cell differentiation and activity, suggesting potential relevance in autoimmune diseases and immunotherapy." (PMID 40963867, 2025).
clear cell renal cell carcinoma (1 paper, 2022). "They showed that MFNG was expressed in the endothelial cells and that the elevated expression of MFNG was also found in clear cell renal cell carcinoma (ccRCC)." (PMID 35335147, 2022).
lung carcinoma (1 paper, 2022). "However, whether MFNG regulates lung cancer tumorigenesis and progression has not been reported." (PMID 36575396, 2022).
tumor (8 papers, 2010 to 2024). "Meanwhile, MFNG expression was linked to gender and tumor recurrence, and it was higher in patients with OS recurrence." (PMID 37496053, 2023). "Several of the GRGs and GRPs commonly correlated with survival in different tumor types are actually associated with specific cells in the stromal compartment (as MFNG in all immune cells, LGALS2 in myeloid cells, ST6GAL1 in B and plasma cells and CHPF and ST3GAL4 for fibroblasts)." (PMID 38384845, 2024). "Importantly, lower tumor expression of MFNG significantly associated with poor CRC prognosis specifically in the group of JAG1-high tumors." (PMID 30065304, 2018). "The expression of MFNG in tumor tissue of STAD and CHOL and the expression of RFNG in tumor tissue of LIHC were also significantly (P < 0.001) higher than in normal tissue." (PMID 37932706, 2023). "Our findings revealed that GATA3 and miR-205-p cooperatively block the transcription of MFNG leading to the inhibition of cell migration and tumor growth in vitro and in vivo." (PMID 35804829, 2022). "As a key modulator of Notch signaling, MFNG plays dual functions in carcinogenesis as it can function as a tumor suppressor or an oncogene depending on the type of cancer." (PMID 35804829, 2022). "Thus, we accessed the exoRBase database to show higher mRNA expression levels of IRF1 and MFNG in exosomes from human blood, compared to that from multiple tumor tissues." (PMID 34277600, 2021). "Some of the tumour suppressor genes identified in our study included Lactotransferrin (LTF), MFNG and SOSTDC1." (PMID 21092330, 2010).
cancer (7 papers, 2016 to 2024). A tumor composed of atypical neoplastic, often pleomorphic cells that invade other tissues. "In conclusion, our pan-cancer analyses have revealed correlations between LFNG, MFNG, and RFNG expressions, with its methylation states, mutations, clinical prognosis, and immune cell infiltration." (PMID 37932706, 2023). "The study found that the deletion or reduced expression level of MFNG gene may lead to changes in cell polarity, which in turn increases the invasion and metastasis ability of cancer cells, thereby affecting the survival rate of patients." (PMID 37932706, 2023). "Most immune cells were negatively correlated with the expression of LFNG, MFNG, and RFNG in pan-cancers, especially T cells." (PMID 37932706, 2023). "Therefore, MFNG may play a unique role in different cancer types." (PMID 36575396, 2022). "Levels of MFNG in this subgroup of tumors also determined the transcriptional status of several Notch target genes such as NKD1, DLX3, EREG, EPHA4, or IL7R, known to be relevant for cancer progression." (PMID 30065304, 2018).
MFNG also shares sentences with these, for which no sentence is quoted: renal cell carcinoma (2 papers); triple-negative breast carcinoma (2); aortic stenosis (1); colon cancer (1); endocervical adenocarcinoma (1); glioblastoma (1); glioma (1); leiomyosarcoma (1); malignant fibrous histiocytoma (1); myxoid/round cell liposarcoma (1); osteosarcoma (1); ovarian carcinoma (1); thymoma (1); uterine corpus endometrial carcinoma (1).